PSMA8 (proteasome 20S subunit alpha 8)
Description:
Component of the spermatoproteasome, a proteasome specifically found in testis that promotes acetylation-dependent degradation of histones, thereby participating actively to the exchange of histones during spermatogenesis. The proteasome is a protein complex that degrades unneeded or damaged proteins by proteolysis, a chemical reaction that breaks peptide bonds. Required for 20S core proteasome assembly, essential for the degradation of meiotic proteins RAD51 and RPA1 at late prophase I and the progression of meiosis I during spermatogenesis. Localizes to the synaptonemal complex, a 'zipper'-like structure that holds homologous chromosome pairs in synapsis during meiotic prophase I.
Synonyms: PSMA7L; MGC26605
Tractability: Small molecule: an approved drug acts on it; a high-quality ligand is known; it belongs to a druggable protein family. PROTAC: ubiquitination databases record sites on it; a small molecule that binds it is known.
Gene: Protein-coding gene on chromosome 18 (26,133,852 to 26,193,355, forward strand). Ensembl gene ENSG00000154611.
Subcellular location: Nucleus
Subcellular location (Human Protein Atlas): Principal piece; Vesicles
Pathways (Reactome):
Metabolism of proteins: Proteasome assembly
Gene Ontology:
Biological process: flagellated sperm motility; meiotic cell cycle; proteasomal protein catabolic process; proteasome-mediated ubiquitin-dependent protein catabolic process; spermatogenesis; protein catabolic process; regulation of meiosis I; regulation of proteasomal protein catabolic process; response to oxidative stress; ubiquitin-dependent protein catabolic process
Cellular component: extracellular exosome; nucleus; proteasome core complex, alpha-subunit complex; spermatoproteasome complex; cytosol; proteasome core complex
Genetic constraint (gnomAD): Loss-of-function variants: 11 observed, 19.82 expected, observed/expected ratio (o/e) 0.55, 90% interval 0.35 to 0.92. The upper end of that interval is the gene's LOEUF score, 0.92, which puts it in group 3 of 6, group 1 being the genes least tolerant of losing a copy. Missense variants: 221 observed, 217.17 expected, observed/expected ratio (o/e) 1.02, 90% interval 0.91 to 1.14. Synonymous variants: 73 observed, 69.28 expected, observed/expected ratio (o/e) 1.05, 90% interval 0.87 to 1.28.
Homologues: Orthologues: chimpanzee PSMA8 (99% identical), macaque PSMA8 (99% identical), dog PSMA8 (96% identical), rabbit PSMA8 (96% identical), guinea pig PSMA8 (96% identical), pig PSMA8 (96% identical), rat Psma8 (96% identical), mouse Psma8 (95% identical), zebrafish psma8 (89% identical), Caenorhabditis elegans pbs-1 (15% identical), Drosophila melanogaster Prosbeta1 (12% identical). Paralogues in human: PSMA7 (84% identical), PSMA4 (39% identical), PSMA2 (37% identical), PSMA5 (36% identical), PSMA1 (34% identical), PSMA3 (32% identical), PSMA6 (29% identical), PSMB7 (19% identical), PSMB4 (18% identical), PSMB10 (17% identical), PSMB9 (16% identical), PSMB6 (16% identical), and 6 more.
Diseases named in the same sentence as PSMA8 in open-access papers:
PSMA8 is named in the same sentence as 12 diseases in open-access papers, as found by Europe PMC text mining. Sharing a sentence is not in itself a finding about the gene and the disease. The quoted sentences say what the papers report.
male infertility (4 papers, 2019 to 2024). The inability of the male to effect fertilization of an ovum after a specified period of unprotected intercourse. "Although they also demonstrated that the deletion of α4s/PSMA8 leads to male infertility in mice, the underlying mechanisms we each provide are complementary." (PMID 33262216, 2021). "Although two other papers also demonstrated that the deletion of α4s/PSMA8 leads to male infertility in mice, the underlying mechanisms in their papers are different from ours." (PMID 33262216, 2021). "For example, spermatocytes are finally arrested in M-phase by disruption of PSMA8 in mice, leading to abnormal spermatogenesis and male infertility." (PMID 38597936, 2024). "PSMA8 deletion delays entry into the M phase by activating phase I proteins; a decrease in PSMA7 stops it at this stage and ultimately causes male infertility." (PMID 37239333, 2023). "Taken together, these finding indicate that spermatocytes lacking PSMA8-associated 20S core proteasomes exhibit delayed progression to M phase and are arrested at this stage, resulting in male infertility in these mice." (PMID 31358751, 2019). "Moreover, PSMA8-null spermatocytes exhibit delayed M-phase entry and are finally arrested at this stage, resulting in male infertility." (PMID 31358751, 2019).
breast carcinoma (3 papers, 2021 to 2025). "High-expressed PSMA family genes (e.g., PSMA2, PSMA3, PSMA4, PSMA6, and PSMA7) in breast cancer tissues are reported to be linked to a poor OS of the cancer, but higher levels of PSMA5 and PSMA8 are indicative of better clinical outcomes." (PMID 41141246, 2025). "This set comprised senescence markers (CDKN1A, LMNB1, MKI67), apoptosis regulators (BCL2, BCL2L1), a highly overexpressed gene (ITGB6), and drug targets (ACTA2, GSDMC, KRT6A, PDE1A, PSMA8), all of which showed strong concordance with our RNA-seq data in all four breast cancer cell lines." (PMID 40312750, 2025).
Alzheimer disease (1 paper, 2023). A progressive, neurodegenerative disease characterized by loss of function and death of nerve cells in several areas of the brain leading to loss of cognitive function such as memory and language. "Using bioinformatics analysis, we found that the mRNA expression levels of frizzled class receptor 6 (FZD6) and proteasomal subunit α4s (PSMA8), which associated with the Wnt signaling pathway and Alzheimer disease, were downregulated in the vitreous of patients with PDR." (PMID 36899334, 2023).
esophageal cancer (1 paper, 2023). A primary or metastatic malignant neoplasm involving the esophagus. "PSMA8 (Proteasome 20S subunit alpha 8), linked to innate immune response pathway and CD pathogenesis, was found altered in around 5% of esophageal cancers." (PMID 36833303, 2023).
infertile (1 paper, 2019). "Using the mouse as a model, we show that loss of PSMA8 leads to infertility in males." (PMID 31437213, 2019).
melanoma (1 paper, 2019). A malignant, usually aggressive tumor composed of atypical, neoplastic melanocytes. "From an organismal perspective, Psma8 transcription is mainly restricted to the human testis and to some tumors like Burkit lymphoma and melanoma (TCGC database)." (PMID 31437213, 2019).
varicocele (1 paper, 2015). A condition characterized by the dilated tortuous veins of the spermatic cord with a marked left-sided predominance. "Our data showed that overexpression of PSMA8 in the unilateral varicocele group indicates the involvement in altered motility and a compromised ability to undergo acrosome reaction." (PMID 25890347, 2015).
cancer (4 papers, 2021 to 2025). A tumor composed of atypical neoplastic, often pleomorphic cells that invade other tissues. "Furthermore, PSMA8 predicts favorable outcomes in cancer and is associated with immune response signaling, which corresponded with our study." (PMID 36035152, 2022). "In contrast, we identified that genes splA/Ryanodine receptor domain and SOCS box containing 1 (SPSB1) and proteasome 20S subunit alpha 8 (PSMA8) are frequently subjected to low CNV in numerous cancer types." (PMID 38794205, 2024).
tumor (2 papers, 2021 to 2024). "After reviewing the literature, we found that the PSMA8 gene is associated with tumor cell invasion and metastasion." (PMID 39764438, 2024).
PSMA8 also shares sentences with these, for which no sentence is quoted: allergic contact dermatitis (1 paper); hematological malignancies (1); type 1 diabetes mellitus (1).